STAT3 (signal transducer and activator of transcription 3)
Diseases named in the same sentence as STAT3 in open-access papers (continued):
Sharing a sentence is not in itself a finding about the gene and the disease.
psoriasis (continued). "IL-17A treated STAT3 overexpressing mouse model might serve as an animal model for psoriasis." (PMID 37465147, 2023). "Therefore, MAPK and STAT3 synergistically promote the development of psoriasis." (PMID 37445960, 2023). "In conclusion, the present study provides evidence that miR-125a-5p may have a therapeutic potential in psoriasis by restoring the suppressive function of Tregs on Th17 cells through targeting STAT3, and on Th1 cells indirectly through targeting ETS-1 and IFN-γ." (PMID 37773129, 2023). "Furthermore, IL-24 from activated T cell-derived microvesicles motivated MCs and excessive MCs activation in psoriasis could produce IL-24, subsequently provoking STAT3 phosphorylation of KCs." (PMID 36242051, 2022). "Thus, STAT3 in keratinocytes is more important for the development of psoriasis." (PMID 35075118, 2022). "Thus, we intended to investigate whether miR-204-5p and STAT3 are engaged in triptolide-mediated psoriasis development." (PMID 36474621, 2022). "Furthermore, ANGPTL4 could promote keratinocyte proliferation and induce inflammatory response via ERK1/2 and STAT3 dependent signaling pathway, resulting in pathological changes in psoriasis." (PMID 35860030, 2022). "In addition, CHALT could also weaken the inflammatory response triggered by IL-6 and JAK/STAT3 signaling pathway in keratinocytes, thereby inhibiting the progression of psoriasis." (PMID 36618400, 2022). "In this study, we found that glycyrrhizin can attenuate the promotion of a-STAT3 induced by SIRT1, which suggests that glycyrrhizin may attenuate the response of keratinocytes to IL-22 by inhibiting the expression of a-STAT3, thereby playing a role in improving psoriasis." (PMID 34044769, 2021). "In summary, our results show that curcumol reduces proliferation and inflammatory response in keratinocytes stimulated with proinflammatory cytokines by inhibiting the JAK1/STAT3 pathway, suggesting that curcumol might provide a potential therapeutic option for the treatment of psoriasis." (PMID 34314383, 2021). "Because STAT3 overactivation has been closely associated with the development of psoriasis, a chronic autoimmune skin disease, we examined whether HCA ameliorates skin lesions in an imiquimod-induced psoriasis-like mouse model." (PMID 33990689, 2021). "Moreover, IL1B and STAT3 were also reported as hub genes in psoriasis and targets of LXJD formula." (PMID 34168554, 2021). "In addition, through the SIRT1-dependent pathway, the inhibition of p-STAT3 and a-STAT3 expression by glycyrrhizin may also be related to the improvement of psoriasis." (PMID 34044769, 2021). "STAT3 is a very crucial signaling molecule in the development of psoriasis because transgenic mice with keratinocytes expressing a constitutively active Stat3 (K5.Stat3C mice) develop a skin phenotype either spontaneously, or in response to wounding, that closely resembles psoriasis." (PMID 32070069, 2020). "Besides MAPK/AP-1 and NF-κB pathways, STAT3 also plays an essential role in psoriasis." (PMID 31495284, 2019). "Thus, MAPK and STAT3 synergistically promote the development of psoriasis." (PMID 31495284, 2019). "Therefore, Hectd3 may be a favorable target for MS, other Th17-related diseases such as psoriasis, or cancer therapy since Stat3 activation is instrumental in their pathogenesis." (PMID 30741923, 2019). "The activation of SIRT1 could effectively inhibit MAPK, NF-κB, and STAT3 phosphorylation, thereby decreasing the expression of downstream genes and secretion of inflammatory cytokines, eventually blocking the development of psoriasis." (PMID 31495284, 2019). "Thus, STAT3 has been aroused as an ideal therapeutic target for psoriasis." (PMID 30279326, 2018). "Furthermore, we determined whether LTP has an effect on STAT3 activation in HaCaT because STAT3 activation is crucial for Th17 cell differentiation and psoriasis pathogenesis." (PMID 29138509, 2017).
psoriasis (continued). "Therefore, Stat3 has been recognized as a therapeutic target for psoriasis treatment." (PMID 26893174, 2016). "Hence, targeting Stat3 is potentially beneficial in the treatment of psoriasis." (PMID 26893174, 2016). "Indeed, a STAT3 dODN has already been demonstrated to resolve lesions in a psoriasis mouse model." (PMID 25883770, 2015). "In conclusion, PLO treatment ameliorated IMQ-induced psoriasis by enhancing antioxidant defenses, and by inhibiting JAK2 and JAK3/STAT3 signaling, supporting its potential as a therapeutic candidate for psoriasis." (PMID 42306466, 2026). "Molecular docking studies targeted psoriasis-related proteins (IL-17, IL-22, IL-23, JAK2, MAPK2, NF-κB, STAT3), revealing strong binding affinities for rutin and quercetin, the extract’s dominant bioactives." (PMID 40806422, 2025). "The IL-23/Th17 axis (IL23R, STAT3) is already targeted in IBD by monoclonal antibodies such as ustekinumab (IL-12/23p40) and risankizumab (IL-23p19), initially developed for psoriasis and later repurposed for Crohn’s disease and ulcerative colitis." (PMID 41154835, 2025). "In lung adenocarcinoma, TMEM9 activates the MEK/ERK/STAT3 pathway and induces vascular endothelial growth factor (VEGF) expression, a pathway also involved in psoriasis." (PMID 41153404, 2025). "Crucially, S1PR3 inhibition reduced both Src and STAT3 activation in vivo, corroborating our in vitro findings and supporting the S1PR3–Src–STAT3 signaling axis as a key driver of psoriasis pathogenesis." (PMID 39833165, 2025). "BBR effectively inhibited IMQ-induced psoriasis-like skin lesions and reduced CDC6 and phosphorylated STAT3 levels in mice." (PMID 39576422, 2025). "STAT1 is another important regulator: its downregulation promotes STAT3 activation and IL-22 production, whereas activation of STAT1 suppresses skin inflammation in imiquimod-induced psoriasis models." (PMID 40906403, 2025). "S1PR3 KO in vitro and in vivo inhibited keratinocyte proliferation and STAT3 phosphorylation, confirming the role of S1PR3 in STAT3 activation and the pathogenesis of psoriasis." (PMID 39833165, 2025). "Reportedly, allicin directly inhibits the IL-17A/F-induced STAT3/NF-κB and TRAF6/MAPK/NF-κB signaling cascades in keratinocytes, thereby attenuating pro-inflammatory feedback and ameliorating psoriasis-like dermatitis." (PMID 40871078, 2025). "It has been shown that human umbilical cord MSC-derived exosomes (hUCMSCs-Exo) are able to alleviate psoriasis-like skin inflammation by suppressing the expression of IL-17, IL-23, CCL20, and STAT3." (PMID 40906403, 2025). "Thematic mapping recovered basic themes (psoriasis, keratinocytes, inflammation), motor themes (miR-146a-5p, exosomes, GAB1), and emerging terms (STAT3, adalimumab)." (PMID 41458345, 2025). "CP has also shown efficacy against psoriasis, an inflammatory skin condition with abnormal keratinocyte activity that exhibit aberrant MAPK, PI3K/Akt, STAT3, and NFκB pathway." (PMID 38785562, 2024). "This signaling program resembles wound healing and psoriasis, and these pathways are well-described as oncogenic in specific contexts, predominantly c-JUN, IL6/JAK/STAT3, and TGFβ." (PMID 39358322, 2024). "In this study, we identified NF-κB, FOXO1, CEBPB, STAT3, and ERK1/2 as the drug targets for the treatment of psoriasis." (PMID 37373186, 2023). "The JAK/STAT3 and JAK/STAT1 signaling pathways play an important role in the development of psoriasis when triggered by IL-6 and IFN-γ, which are produced by dendritic cells and T-lymphocytes." (PMID 36838711, 2023). "Our findings suggest that lncRNA UCA1 promotes keratinocyte-driven inflammation in psoriasis by targeting and inhibiting METTL14 protein and then activating the HIF-1α/STAT3 and NF-κB signaling pathways." (PMID 37076497, 2023).
psoriasis (continued). "Previous research has demonstrated the inhibitory effect of GA on pro-inflammatory transcription factors, such as STAT3, RORγt, and NF-κB, or cytokines as IL-1β and TNF, which contribute to psoriasis development." (PMID 36754913, 2023). "Therefore, STAT3 may be a potential target for psoriasis therapy." (PMID 36838711, 2023). "In a mouse model of psoriasis, researchers observed decreased levels of SIRT2 and increased activation of PKM2 through the acetylation and phosphorylation of STAT3." (PMID 37445960, 2023). "In our study, we treated psoriasis-induced mice and IL-22- or TNF-α-stimulated HaCaT cells with SFN and subsequently measured the activation status of the STAT3 and NF-κB pathways." (PMID 38007430, 2023). "Accordingly, Stat3 signalling is elevated in both psoriasis and IMQ-induced psoriasis-like lesions, according to several studies." (PMID 37663384, 2023). "The transcription factor STAT3, a member of the family of signal transducers and activators of transcription (STAT), has emerged as one of the key players in the pathogenesis of psoriasis." (PMID 37226685, 2023). "ETS-1, STAT3, and IFN-γ are important regulators involved in the differentiation of Th1 and Th17 cells, and their relationship with psoriasis and miR-125a-5p remains to be elucidated." (PMID 37773129, 2023). "Overall, the application of ADE relieves psoriasis-like skin inflammation possibly by regulating the Akt/mTOR and JAK2/STAT3 signaling pathways, making it an effective alternative for psoriasis therapy." (PMID 36501124, 2022). "The complex pathogenesis of psoriasis is regulated by the interplay between several signaling pathways, including JAK2/STAT3 and Akt/mTOR." (PMID 36501124, 2022). "Presently, the results in our study showed that the protein expression of p‐JAK/JAK and p‐STAT3/STAT3 was sharply increased in psoriasis mice, and etanercept treatment blocked the expression of p‐JAK/JAK and p‐STAT3/STAT3." (PMID 36444619, 2022). "To investigate the mechanisms of etanercept on IMQ–induced psoriasis mice, we detected the expression of JAK/STAT3 pathway." (PMID 36444619, 2022). "Previous studies have reported that STAT3 and JNK play crucial roles in regulating immune responses and participate in the pathogenesis of psoriasis." (PMID 35586566, 2022). "Compound 1 also clearly inhibited the phosphorylation of STAT3, which regulates the expression of cytokines, and CCL20 chemokines in TNF-α /IL-17A/ IFN-γ induced the psoriasis condition." (PMID 36015080, 2022). "We found several regulators that have previously been reported to be increased in psoriasis, such as CRABP2 (a carrier protein for retinoic acid signaling pathways) and STAT3 (a central regulator of various immune responses)." (PMID 35874668, 2022). "In psoriatic epidermis, Trim21 was found overexpressed and induced activation of STAT3 through ubiquitylating and stabilizing KRT17 in keratinocytes, thus promoting the development of psoriasis." (PMID 35075118, 2022). "We found that psoriasis and AD share many DEGs and pathways, but also identified regulators, such as FOXE1, FOXM1, STAT3 and SOX7, and discovered a gene regulatory network unique for psoriasis." (PMID 35874668, 2022). "Collectively, apremilast effectively alleviated the psoriatic phenotype of K5.Stat3 transgenic mice, further substantiating PDE4 inhibitor-efficiency in targeting key clinical, histopathological and inflammatory features of psoriasis." (PMID 34884681, 2021). "Therefore, we speculate that glycyrrhizin reduces the expression of IL-17A by inhibiting the expression of STAT3, while the low expression of IL-17A further weakens the expression of STAT3 in keratinocytes, thereby forming a positive feedback pathway, which is beneficial for improving psoriasis." (PMID 34044769, 2021).
psoriasis (continued). "In conclusion, our work demonstrates that hyperforin alleviates IMQ-induced inflammation in psoriasis through suppressing the immune responses exerted by IL-17 A–producing γδ T cells and related cytokines by modulating MAPK/Stat3 pathways." (PMID 34025642, 2021). "In conclusion, hyperforin alleviates IMQ-induced inflammation in psoriasis through suppressing the immune responses exerted by IL-17 A-producing γδ T cells and related cytokines by modulating MAPK/STAT3 pathways." (PMID 34025642, 2021). "In mice T-cells and dendritic cells had increased STAT3/RORC expression and patients with psoriasis had elevated level of RORC (RORG-t isoform)." (PMID 34445309, 2021). "Given the importance of STAT3 in psoriasis, HCA-mediated targeting of the PKM2-STAT3 axis represents an effective strategy for treating this disease, as well as other Th17 cell-mediated inflammatory diseases." (PMID 33990689, 2021). "A total of 389 significant genes were common to both hepatitis C and psoriasis, which mainly involved IL6, TNF, IL10, ALB, STAT3 and CXCL8." (PMID 34215260, 2021). "Agents that potentiate Tregs, such as STAT3 inhibitors, butyrate, HDAC inhibitors, or probiotics/prebiotics, are under development for the treatment of psoriasis." (PMID 34501328, 2021). "The result showed that five gene sets were significantly enriched in psoriasis samples, including inflammatory response, TNF-α signaling via NF-κB, IFN-α/β response and IL-6/JAK/STAT3 signaling." (PMID 33613635, 2021). "For example, activation of STAT3 by IL-22 is involved in the proliferation of keratinocytes, and activation of STAT3 by IL22 and IL-17A is involved in the induction of keratin 17, which is overexpressed in psoriasis." (PMID 34679602, 2021). "Thus, miR-22 may be inhibited by STAT3 mediated pathogenesis in psoriasis." (PMID 32811699, 2020). "STAT3, p-STAT3, UBE2N and CDK6 are downregulated by the overexpression of hsa-miR-4516, which is consistently upregulated in psoriasis and induces apoptosis in HaCaT cells." (PMID 32785106, 2020). "Of particular note is the acute up-regulation of Il17f (63-fold), in line with the central role of Stat3 in Th17-mediated pro-inflammatory responses and its implication in dermal disorders including HIES and psoriasis." (PMID 33332446, 2020). "In recent years, a growing number of studies have focused on the development of new drugs for psoriasis, including JAK inhibitors, Stat3 inhibitors, PDE4 inhibitors, TRK inhibitors, and AhR agonists." (PMID 33834028, 2020). "p65 and STAT3 cooperatively recruit intercellular adhesion molecule (ICAM)-135, which play an important role in inflammatory cell migration in psoriasis; moreover, PPL reduced LPS-induced ICAM-1 expression." (PMID 31924750, 2020). "Radix arnebiae can be used both internally and externally to treat psoriasis, which decreases IL-17-induced VEGF expression by the inhibition of JAK2/STAT3 signaling and exerts an anti-inflammatory effect via proteasome inhibition." (PMID 33551804, 2020). "Furthermore, inhibition of Stat3 with decoy oligonucleotides successfully inhibited disease development and even reversed disease severity showing that Stat3 may be an important regulator of genes in keratinocytes in the development of psoriasis cooperating with T cells." (PMID 31447854, 2019). "We next analyzed the expression of STAT3 and STAT5 phosphorylation (p‐STAT3, p‐STAT5) by immunofluorescence in ear sections of psoriasis‐like mice treated with anti‐TSLP or IgG." (PMID 31556482, 2019). "The JAK1/JAK2/STAT1 and JAK1/TYK2/STAT3 pathways triggered by IFN-γ and IL-22, respectively, are aberrantly activated in psoriasis, as highlighted by the peculiar STAT1 and STAT3 signatures in psoriatic skin lesions." (PMID 30581877, 2018). "Il-22, a critical psoriasis-related cytokine, increases CD147 expression in vitro and in vivo through Stat3." (PMID 28272440, 2017).
psoriasis (continued). "A ChIP assay confirmed that Stat3 binds to the CD147 promoter, which facilitated increases in CD147 expression in psoriasis-like skin lesions." (PMID 28272440, 2017). "Our results indicate that psoriasis is mainly a JAK3 and JAK1 driven disease with a predominance of STAT3 signaling." (PMID 27711196, 2016). "Regarding STATs, qPCR results indicated overexpression of STAT3 (p = 0.052) and STAT1 (p = 0.005) in psoriasis." (PMID 27711196, 2016). "HIF-1α and its regulators (HDAC-1, HDAC-7, VHL-E3, PHD2, LL-37, HIF-1β, mTOR, miR-210, RORγt, STAT3, and IL-13Ralpha, as well as glycolysis enzymes) could be important pharmacological targets to restore the lack of regulation in the angiogenesis and in immunological processes involved in psoriasis." (PMID 26136626, 2015). "Several TFs/uDBPs additionally showed altered expression in blood from psoriasis patients (increased: JUNB, STAT3, DTL, CAT; decreased: CUX2, ZNF559, AVEN, RUVBL1, RAN)." (PMID 25883770, 2015). "In conclusion, we here identify a central role for PPARβ/δ in the pathogenesis of psoriasis and identify IL1 and STAT3 signalling as novel pathways regulated by PPARβ/δ." (PMID 20300524, 2010). "First, the two EGF-family ligands TGFα and HB-EGF, previously identified as a direct transcriptional target of PPARβ/δ, are highly upregulated in PPARβ/δ as well as in psoriasis, suggesting that EGF-receptor activation contributes to STAT3 phosphorylation." (PMID 20300524, 2010). "Similarly, in psoriasis, TOPK regulates neutrophil chemokines such as CXCL1, CXCL2, and CXCL8 by activating STAT3 and NF-κB p65 in keratinocytes, thereby promoting neutrophil infiltration and psoriasis progression." (PMID 41362722, 2026). "On the other hand, the specific absence of STAT3 in keratinocytes reduces psoriasis-like dermatitis." (PMID 40427630, 2025). "In addition, ChIP-seq experiments have identified multiple transcription factor peaks, including AP2-, AP2-, STAT1, STAT3, as well as FOXA1, which has binding sites overlapping with two loci (2q13 for acne and 2q11.2 for psoriasis)." (PMID 39975900, 2025). "Various studies indicate that the mTOR and STAT3 pathways are significant for psoriasis development; however, in mouse models, mTORC2, not STAT3, deletion results in a mitigated psoriasis profile and changes in the γδ17 T cells profile." (PMID 40276509, 2025). "Additionally, miR-125b also regulates inflammatory cytokines such as STAT3 and TNF-α, crucial to the inflammatory cascade in psoriasis." (PMID 39997616, 2025). "Our results indicated that sodium orthovanadate treatment did not influence the P-STAT3 levels in HaCaT cells, compared to IL-6 and CYM treatment, suggesting that phosphatase was not involved in the S1PR3-mediated STAT3 activation in psoriasis." (PMID 39833165, 2025). "In psoriasis, MSC-derived EVs show the most consistent therapeutic signal and the broadest mechanisms, attenuating dendritic-cell IL-23 production, suppressing keratinocyte STAT3 signaling, and (topically) limiting complement/NETosis." (PMID 41226338, 2025). "It is highly interesting, that STAT3 overexpression in keratinocytes was sufficient to induce psoriasis marker expression in full-thickness skin models but not in epidermis models." (PMID 40678130, 2025). "In our study, it appeared that PSVII could downregulate p-STAT3, NFκB, p-NFκB, IKKβ, p-IKKβ, and IκBα, offering preliminary evidence that PSVII likely modulates psoriasis by targeting the STAT3/NFκB signaling pathway." (PMID 40405066, 2025). "STAT3 overexpressing skin models without psoriatic stimuli resembled histologically normal skin but expressed abnormal high levels of the psoriasis marker S100A7." (PMID 40678130, 2025). "STAT3, CEBPB, and NF-κB are recognized as significant biomarkers in the pathogenesis of psoriasis and may serve as potential drug targets for its treatment." (PMID 40487290, 2025).